PROKR2 (prokineticin receptor 2)
Diseases named in the same sentence as PROKR2 in open-access papers (continued):
Sharing a sentence is not in itself a finding about the gene and the disease.
pituitary disease (2 papers, 2017 to 2023). "Although we report on heterozygous mutations in both PROKR2 and WDR11 in the same individual, each of these genes has previously been implicated with another gene mutation as the basis for a digenic pituitary disease." (PMID 28453858, 2017). "In human studies as well as in animal models, PROKR2 haploinsufficiency seems not to account for the PSIS phenotype, hence raising the need for a “second hit,” either genetic or environmental, to produce pituitary disease." (PMID 28453858, 2017).
psychosis (2 papers, 2011). "For example, we detected the associations between prokineticin 2 receptor (PROKR2) and not only mood disorders including MDD and BP but also METH dependence and METH-induced psychosis in the Japanese population." (PMID 21886578, 2011).
5-alpha-reductase deficiency (1 paper, 2017). "These include three patients (i.e., P09, P22, P28) with 5-alpha-reductase deficiency due to biallelic mutations of the SRD5A2 gene, and four patients with idiopathic hypogonadotropic hypogonadism due to mutations of KAL1 (i.e., P27, P32), PROKR2 (P03) or GNRHR (P13)." (PMID 28295047, 2017).
chlamydial infection (1 paper, 2025). "According to certain studies, a history of chlamydial infection causes the formation of a protein called PROKR2, which increases the likelihood that a pregnancy will involve implantation in a tubes." (PMID 40471945, 2025).
choanal atresia (1 paper, 2012). Choanal atresia (CA) is a congenital anomaly of the posterior nasal airway characterized by the obstruction of one (unilateral) or both (bilateral) choanal aperture(s), with clinical manifestations ranging from acute respiratory distress to chronic nasal obstruction. "Developmental defects of GnRH neurons and the olfactory bulb are associated with hyposmia, rarely associated with the clinical phenotypes of synkinesia, cleft palate, ear anomalies, or choanal atresia, and may be due to mutations of KAL1, FGFR1/FGF8, PROKR2/PROK2, or CHD7." (PMID 22229029, 2012).
cleft lip (1 paper, 2024). Congenital defect in the upper lip where the maxillary prominence fails to merge with the merged medial nasal prominences. "One of the KS patients also carried the PROKR2 (p.Y113H) mutation, which has similar clinical manifestations to the patients in this study; the other KS patient who carried both FGFR1 (p.Gly348Glu) and RUVBL2 (p.Arg71Trp) only showed non-reproductive symptoms associated with cleft lip and palate." (PMID 38628584, 2024).
cognitive decline (1 paper, 2025). "Prokr2 is up‐regulated in models of circadian disruption, which is itself implicated in cognitive decline." (PMID 40944384, 2025).
endometrial polyp (1 paper, 2025). A benign nodular lesion protruding above the surface of the endometrium. "The results indicate that PROKR1 and PROKR2 exhibit significant changes in expression between women with endometrial polyps and controls, with PROKR1 being upregulated and PROKR2 downregulated." (PMID 39915377, 2025). "Overall, the figure suggests that while PROKR1 and PROKR2 show the most significant changes, other genes like PROK1, PROK2, and HOXA10 exhibit smaller or non-significant alterations, highlighting the importance of certain prokineticins in the pathology of endometrial polyps." (PMID 39915377, 2025).
growth disorders (1 paper, 2023). "All these variants were identified in genes already associated with growth disorders: PROKR2 (N = 2), PTPN11 (N = 6), ANKRD11 (N = 1), NPR2 (N = 1), NF1 (N = 1), ACAN (N = 1), GH1 (N = 1), FBN1 (N = 1), COMP (N = 1), IGF1R (N = 1), ARID1A (N = 1), and CASR (N = 1)." (PMID 37605180, 2023).
Hypoglycemia (1 paper, 2025). A decreased concentration of glucose in the blood. "In two previously reported cases, patients with mutations in PROKR2 presented with seizures that were temporally associated with episodes of hypoglycemia." (PMID 41282487, 2025).
myoma (1 paper, 2025). "The downregulation of PROKR2 suggests a possible disruption of the prokineticin signaling pathway, while the observed decrease in HOXA10 expression may be linked to myoma uteri and could influence fertility." (PMID 39915377, 2025).
neuroendocrine disorder (1 paper, 2023). A disease or disorder that affects the neuroendocrine gland, any of the organized aggregations of cells that function as secretory or excretory organs and that release hormones in response to neural stimuli. "in 2006, many studies have reported PROKR2 genetic alterations in patients with neuroendocrine disorders." (PMID 36843573, 2023).
Onset (1 paper, 2019). The age group in which disease manifestations appear. "In particular, in three patients presenting with mild, adult-onset disease we found variants (PROKR2 R85H, FGF8 P26L, and HS6ST1 R382W) already reported to impair protein activity in several functional characterization or to segregate with the phenotype, or both." (PMID 30669598, 2019).
cancer (1 paper, 2015). A tumor composed of atypical neoplastic, often pleomorphic cells that invade other tissues. "G protein-coupled receptors (PROKR1 and PROKR2) are the receptors for PROK1 and are expressed in the endothelial cells and cancer cells themselves." (PMID 25788276, 2015).
endocrine disorders (1 paper, 2023). "More recently variants in PROKR2 have been linked to several other endocrine disorders." (PMID 36843573, 2023).
PROKR2 also shares sentences with these, for which no sentence is quoted: Anosmia (6 papers); Micropenis (4); genetic disease (2); holoprosencephaly (2); Noonan syndrome (2); adenocarcinoma (1); Alzheimer disease (1); bipolar disorder (1); ciliopathies (1); citrullinemia (1); colorectal cancer (1); congenital hypopituitarism (1); deafness (1); Ehlers-Danlos syndrome (1); Ellis-van Creveld syndrome (1); glioma (1); Hypertension (1); irritable bowel syndrome (1); kidney disease (1); Male pseudohermaphroditism (1); malignant glioma (1); meningioma (1); Miscarriage (1); mood disorder (1); myocardial infarction (1); nemaline myopathy (1); ovarian failure (1); preeclampsia (1); renal agenesis (1); septal heart defects (1).
A further 4 diseases each share a sentence with PROKR2 in 1 paper.